AURKA (aurora kinase A)
Diseases named in the same sentence as AURKA in open-access papers (continued):
Sharing a sentence is not in itself a finding about the gene and the disease.
cancer (continued). "However, although some of these findings were replicated in multiple immortalized and cancer cell lines, it is not clear how cells use this EGFR-mediated AURKA transcriptional regulation to adapt their proliferation rates to EGF signalling." (PMID 36067794, 2022). "Among the identified candidate genes, AURKA, SKA3, and DSN1, which are involved in cell cycle transition, cell growth, and proliferation, were progressively up-regulated in paired non-neoplastic colon tissues, adenomas, and carcinomas." (PMID 27329586, 2016). "Furthermore, while life-threatening chemoresistance, EMT and cancer stem cell phenotypes define CRPC, the mechanism by which AURKA might facilitate these events has not been examined." (PMID 32178290, 2020). "Despite the degree of uncertainty in our measurements, these observations may be consistent with an effect of APA on AURKA mRNA stability in READ, BRCA, and UCEC, and lack of correlation in LUAD, KIRC, and KIRP instead possibly points to an effect on AURKA translation in these cancers." (PMID 39527514, 2024).
tumor (592 papers, 2002 to 2026). "PTEN, a frequently mutated tumour suppressor, had transcriptional patterns associated with several tumour types, with AURKA emerging as the second most important feature in classification." (PMID 40775769, 2025). "Recent studies have demonstrated that AURKA can not only promote tumor progression but is also associated with drug resistance." (PMID 40718709, 2025). "CD38, linked to growth arrest through apoptotic pathways, and AURKA are targeted by alisertib to inhibit AR-mediated tumor growth." (PMID 40656519, 2025). "The results demonstrated that AURKA expression exhibited a positive correlation with tumor malignancy and high expression was associated with poor prognosis." (PMID 40718709, 2025). "AURKA is a serine/threonine kinase, which has been implicated in the initiation of various tumor types, and its aberrant activation is an important driver of the malignant phenotype of tumors." (PMID 41471272, 2025). "By analyzing different datasets from TCGA as well as combined GEO data, we found that AURKA-high patients had a faster biochemical relapse (BCR) and the AURKA-high cluster has a higher percentage of tumor-associated macrophage and Treg cell in TIME." (PMID 40718709, 2025). "The small molecule, selective AURKA inhibitor alisertib (MLN8237) inhibits tumor cell proliferation and causes apoptosis, differentiation, or senescence." (PMID 40336841, 2025). "By modulating the expression or activity of key ncRNAs implicated in AURKA regulation, therapeutic interventions can effectively impede tumor development and progression and therefore improve prognosis." (PMID 39598228, 2024). "Tumor cells undergo metabolic reprogramming, and AURKA has been implicated in the regulation of multiple metabolic pathways in tumors." (PMID 38521813, 2024). "It has been stated that aurora kinase A (AURKA) has a major role in cell cycle progression, tumor development, and treatment resistance, and it is associated with a dismal prognosis." (PMID 39057054, 2024). "We discovered that higher Aurora-A positive tumor cell counts (by IHC) and AURKA mRNA expression associated with young age at diagnosis, aggressive tumor characteristics, the basal-like phenotype, and high risk of recurrence." (PMID 39198859, 2024). "In conclusion, our results demonstrate associations between high Aurora-A/AURKA expression and young age, as well as with aggressive tumor features including increased tumor cell proliferation." (PMID 39198859, 2024). "In the METABRIC validation cohort, we also found an association between high AURKA mRNA and large tumor size." (PMID 39198859, 2024). "In SMARCA4-deficient tumor cells, the activity of AURKA is necessary for mitotic spindle assembly and cell survival, and it has been demonstrated that the AURKA inhibitor (VX-680) induces tumror cells death in vitro and in mouse vivo assays." (PMID 38347129, 2024). "The activation of many pathways associated with tumor progression was significantly upregulated in the AURKA-high-expression group compared to that in the AURKA-low-expression group, and these included the cell cycle, mTORC1 signaling, and MYC_TARGETS_V2." (PMID 39585848, 2024). "In this study, we employed CRISPR metabolic screens to find specific tumor subtypes harboring metabolism-related gene mutations that exhibit sensitivity to AURKA inhibitor MLN8237." (PMID 38521813, 2024). "Previous studies have identified specific mutation types associated with tumor sensitivity to AURKA inhibitors, such as RB1 deficiency or loss of SMARCA4 or ARID1A." (PMID 38521813, 2024). "Combined, these data indicate that synergistic targeting of KIF11 and AURKA with specific inhibitors causes a significant delay in tumor growth and improved overall survival compared to single drugs alone." (PMID 37894278, 2023).
tumor (continued). "In our study, we further investigated AURKA expression by IHC in a series of samples from primary IBC and observed that higher expression levels were associated with poor prognosis, underlying a possible more complex role of AURKA on tumor progression." (PMID 36717329, 2023). "In terms of DSS, AURKA expression was associated with 24 tumor types, with higher AURKA expression acting as a protective factor in COAD (p=0.003), OV (p=0.02), and STAD (p=0.04)." (PMID 37965456, 2023). "Overexpression of AURKA has been linked to oncogenic transformation, including chromosomal instability and disruption of multiple oncoprotein regulatory pathways and tumor suppressors." (PMID 37333985, 2023). "We next investigated publicly available databases to assess the RNA expression of transcripts encoding for KIF11, KIF15, TPX2, and AURKA in EWS patient tumor samples using BioGPS (E-GEOD-12102)." (PMID 37894278, 2023). "Upon reviewing the literature, we noticed that AURKA was closely associated with tumor angiogenesis with positive effect on VEGFA transcription and glucose metabolism." (PMID 36977984, 2023). "Then, we applied a multivariate Cox regression analysis adjusting for tumor size, lymph node status, metastatic status, and expression of the AURKA gene as a reporter of the proliferation process, associated with survival in multiple cancers." (PMID 37730697, 2023). "AURKA is significantly upregulated in a wide range of tumor tissues, and increased expression in LUAD is associated with worse treatment outcomes, with individuals with this characteristic having a lower OS rate." (PMID 36311724, 2022). "For instance, the Aurora kinase A SNP rs6024836 AG + GG is related to an earlier tumor stage if combined with the presence of an EGFR mutation, L858R expression and exon 19 in-frame deletion." (PMID 36011604, 2022). "By contrast, an increase in BIM and PTEN led to changes in BIM/Bcl-2 and PTEN/AURKA and, consequently, caused apoptosis which inhibited tumor growth." (PMID 36678556, 2022). "This gene has been suggested as a tumor suppressor in high-risk NB through destabilization of AURKA and MYCN." (PMID 36306349, 2022). "It is well known that overexpression of AURKA is associated with tumor proliferation and chromosomal instability." (PMID 33573176, 2021). "Overexpression and amplification of AURKA in HCC have been associated with aggressive tumor characteristics, chemoresistance, and poor prognosis in HCC, indicating that AURKA plays a significant role in HCC." (PMID 34337035, 2021). "The abnormal expression of AURKA can lead to chromosomal abnormalities and instability of the cell genome, which is a risk factor for tumor formation." (PMID 34917126, 2021). "The other involves the generation of a unique cellular dependency on AURKA functions for their survival when a tumor suppressor is mutated." (PMID 34050264, 2021). "The AURKA gene also showed concordance and high frequency of somatic mutation in most tumor/plasma pairs in women being further associated with tumor recurrence." (PMID 34680380, 2021). "AURKA is overexpressed in a variety of different tumours and has been implicated in cell transformation and centrosome amplification." (PMID 34062959, 2021). "It has been reported that overexpression of EGFR and AurkA in tumor tissues is a risk factor associated with poor disease-free survival and therapy resistance." (PMID 35047986, 2020). "The high AURKA expression pattern possibly explains the high mitotic and proliferative activity, rather found in more aggressive tumours with higher risk of metastatic spread." (PMID 30700254, 2019). "Aurora kinase A (AURKA) is highly expressed in ATRT because of the loss of the INI1 tumor-suppressor gene." (PMID 30249036, 2018).
tumor (continued). "During tumor progression, deregulated activation of Aurora A kinase (AURKA) is functionally linked to epithelial-to-mesenchymal transition (EMT) reprogramming and expansion of a subpopulation of tumor-initiating cells harboring a CD44+/CD24low/− phenotype." (PMID 29289986, 2018). "AURKA over-expression is reported strongly associated with tumor grade and proposed with prognostic value for disease progression." (PMID 28754978, 2017). "In term of the role of mitotic regulators, deletion of AURKA caused mitotic spindle assembly and chromosome segregation failure, subsequently resulted in genetic instability and a significantly increased tumor incidence." (PMID 28147341, 2017). "AURKA overexpression has been associated with aneuploidy, and is a good marker of tumor progression and prognosis." (PMID 27355345, 2016). "GGI, a gene signature that mainly measures tumor proliferation, was highly correlated with Oncotype DX, Gene70, modules describing proliferation (AURKA) and PTEN loss, and MYC and IGF1 pathway activation." (PMID 26934123, 2016). "Immunohistochemical staining showed that overexpression of AURKA was significantly associated with tumor grade (P<0.05) and poor histologic differentiation (P<0.05)." (PMID 25625960, 2015). "In ductal breast cancer, AURKA overexpression is strongly associated with the tumor grade and is therefore of prognostic value for the progression of the disease." (PMID 24876664, 2014). "AURKA is a kinase known to be implicated in the regulation of cell cycle progression and has been associated with different tumor types and treatment responses." (PMID 24947308, 2014). "Despite the complexity of its functions in tumors, levels/distribution of RHAMM isoforms have diagnostic or prognostic value such as identifying which tumor types are sensitive to targeted therapy (e.g., AURKA inhibitors)." (PMID 25157350, 2014). "We correlated increased AURKA-CN in mCRC tumours with KRAS mutation status, overall and progression-free survival (OS, PFS)." (PMID 22240781, 2012). "Sixty-one mCRC tumours were analysed for AURKA-CN using q-PCR, and KRAS mutation status by direct sequencing." (PMID 22240781, 2012). "Principal common CNAs were the well known MYC-associated gain and RB1/INTS6-associated loss that occurred in all mouse and human tumor groups, and the AURKA-associated gain occurred in BRCA2-related tumors from both species." (PMID 20735817, 2010). "Our data indicate that amplification of the MYC locus and loss of the RB/INTS6 locus occurs in all mouse and human tumor groups, and that AURKA amplification occurs in mouse and human BRCA2-mutated tumors." (PMID 20735817, 2010). "Elevated gene expression for AURKA is associated in a number of tumours with high-level amplification of the gene." (PMID 16222316, 2005). "Additionally, as the gene encoding the well‐known oncogenic protein Aurora A, AURKA is significantly upregulated in tumour tissues across multiple datasets (GSE104958, GSE130078, GSE52622, GSE53624, TCGA‐ESCA)." (PMID 40702875, 2025). "Indeed, alisertib binding to AURKA induces a conformational change in its activation loop that disrupts its binding to N-Myc, causing N-Myc degradation and tumor regression." (PMID 39334449, 2024). "In contrast, tumor-associated variants of VHL are defective in ubiquitinating AURKA." (PMID 39334449, 2024). "AURKA’s close association with immune cell infiltration, promoting tumor progression." (PMID 37965456, 2023). "AURKA is a low episodic tumor susceptibility gene regulator and centrosome in the cell cycle." (PMID 36984548, 2023). "Out of the 55 upregulated genes, a 5 gene-signature (CDK1, EZH2, CCNB1, CCNA2, and AURKA) involved in cell regeneration was positively correlated with the status of tumor hypoxia and clustered with stemness-associated genes, as recognized by Parametric Gene Set Enrichment Analysis (PGSEA)." (PMID 37189841, 2023). "An SNV in the gene encoding AURKA was identified in only one of these tumors (tumor 8)." (PMID 35563252, 2022).
tumor (continued). "In addition, the presence of EGFR mutations and the single nucleotide polymorphism (SNP) of Aurora kinase A is associated with earlier tumor stage of the lung adenocarcinoma." (PMID 36011604, 2022). "AURKA expression was closely associated with tumor risk stratification (P < 0.001)." (PMID 34332577, 2021). "Thus, amplification and overexpression of AURKA were strongly associated with several tumor risks, particularly evident in certain gene polymorphisms." (PMID 35201446, 2021). "Thus, although the investigations of how these three AURKA SNPs impact tumor risk are still preliminary, the probability that these SNPs affect CNS tumors cannot be excluded." (PMID 35201446, 2021). "The genetic polymorphism of AURKA can influence its activity, in which a lower kinase activity of AURKA resulting from the different SNP could lead to genomic instability and neoplasm." (PMID 33050100, 2020). "Al-Khafaji and colleagues demonstrated that, except AURKC, all other genes examined showed increased RNA gene expression in NSCLC tumor tissues compared to normal lung tissues, and only AURKA was significantly associated with a poor prognosis in NSCLC patients." (PMID 33202573, 2020). "Due to their regulatory role in the expression of tumor associated genes at post-translational level, we proposed that human argonaute protein (hAgo2) may regulate the expression of AURKA via hsa-miR-32-3p." (PMID 33245732, 2020). "AURKA causes genome instability in a variety of tumor cells." (PMID 30944378, 2019). "Overexpression of AURKA has been linked to the development of some types of tumors, and several studies have correlated its expression to poor differentiation, high tumor aggressiveness, and lymph node metastasis." (PMID 31647033, 2019). "Based on previous reports, we speculated that the AURKA rs8173 might reduce the risk of WT by inhibiting the proliferation and migration of tumor cells through the LIN28B-RAN-AURKA-MYCN signaling pathway." (PMID 31636670, 2019). "Gene expression levels measured relative to the adjacent normal cortex sample revealed numerous oncogenic driver genes with >2-fold higher expression in the tumour and clone samples, including genes encoding AURKA/B, CDK4/6, FGFR1, AKT1/2, MTOR, MET, PIK3C2A, WNT5A, SFRP4, and MYC." (PMID 30736342, 2019). "Amplification of AURKA causes chromosomal instability that may help tumor cells acquire invasive and metastatic phenotypes." (PMID 25625960, 2015). "Because miRNAs play a regulatory role in the tumorigenesis process and can regulate the expression of tumor associated genes, we proposed that tanshinones may regulate the expression of AURKA via adjusting the expression of related miRNAs." (PMID 26036635, 2015). "The utility of these drugs in NF1-deficient tumours may be worth investigating, especially in combination with Ras or AURKA inhibitors, which may have synergistic effects." (PMID 25026295, 2014). "In addition a member of the Aurora kinase family AURKA (closely associated with AURKB) involved in tumor progression has been found to be over expressed in smoking-related tumors." (PMID 22952714, 2012). "In addition, AURKA correlated with the proliferation metagene (R=0.880; P<0.001), showed a positive association with grade (P<0.001), tumor size (P<0.001) and HER2 (P<0.001), and was inversely associated with ER status (P<0.001)." (PMID 23186136, 2012). "Additionally, other findings suggest that besides being associated with cellular senescence, the AURKA gene can drive tumor progression through the LIN28B-RAN-AURKA signaling pathway, and it also plays a role in maintaining N-MYC stability in MYCN-amplified NB." (PMID 39135779, 2024). "Importantly, FAF1 phosphorylation by AURKA does not regulate FAF1 levels, but phosphorylated FAF1 triggers AURKA ubiquitylation, indicating that FAF1 loss may cause AURKA upregulation in tumor tissues." (PMID 39334449, 2024).